NSUN2 (NOP2/Sun RNA methyltransferase 2)
Diseases named in the same sentence as NSUN2 in open-access papers (continued):
Sharing a sentence is not in itself a finding about the gene and the disease.
cancer (continued). "Notably, NSUN2, a 5‐methylcytosine RNA methyltransferase, has been reported to function as an indicative regulator of the cell proliferation and metastasis observed in diverse cancer types." (PMID 37228185, 2023). "However, how m5C modification and NSUN2 promote cancer, and how they function through YAP still remains largely unknown." (PMID 36123390, 2023). "Our study provides the compelling evidence that lactate can serve as a signaling molecule to lactylate and activate NSUN2 catalyzing m5C formation and maintaining mRNA stability of GCLC, by which cancer cells can avoid ferroptotic cell death under acidic TME." (PMID 39742570, 2025). "Existing basic experiments indicate that NOP1, NSUN2, NSUN3, and NSUN4 predominantly promote the majority of cancers, while NSUN5, NSUN6, and NSUN7 demonstrate context-dependent effects—promoting some cancers but inhibiting others." (PMID 41462962, 2025). "Targeting NSUN2 and its downstream signaling axes, such as TIAM2, FSP1, UBE2S, and PHGDH, holds promise for improving treatment responses in cancer patients." (PMID 41256859, 2025). "Nsun2-i4, a small-molecule inhibitor of NSUN2, downregulates the m5C modification on ENO1 mRNA, leading to reduced glycolysis and enhanced efficacy of cancer immunotherapy." (PMID 41373022, 2025). "And we found that NSUN2 has a relative middle expression in A549 and H1299 cell lines among all the NSCLC cell lines according to Cancer Cell Line Encyclopedia (CCLE) database recorded." (PMID 38403250, 2024). "Employing the TCGA dataset, the mRNA expression levels of two primary mRNA m5C methyltransferases, NSUN2 and NSUN6, in 43 pairs of adjacent and cancer tissues from patients with HNSCC was investigated." (PMID 39595099, 2024). "In this study, the expression of NSUN2 in different cancer types was first analyzed with the TIMER database and UCSC website, and we found that NSUN2 was highly expressed in most types of tumors compared with normal tissues." (PMID 37769000, 2023). "NSUN2 was found to be a downstream regulator of MYC and promotes cancer cell proliferation by RNAPIII methylation." (PMID 33922187, 2021). "The writers of m5C and m7G, NSUN2 and METTL1 are both tRNA modifiers which are found concurrently overexpressed in human cancers." (PMID 32194861, 2020). "The human homologue of yeast Trm4, namely TRM4, MISU or NSUN2, can methylate 5-cytosine in various non-coding RNAs7, 8 and plays an important role in the regulation of stem cell development and cancer cell proliferation and metastasis." (PMID 29563491, 2018). "NSUN2 (SAKI) has been reported to be overexpressed and with gain in gene copy-number in various of human cancers." (PMID 25233213, 2014). "A simultaneous overexpression of NSUN2 and METTL1 is widely observed among human cancers suggesting that targeting of both proteins provides a novel powerful strategy for cancer chemotherapy." (PMID 25233213, 2014). "Here, we provide evidence that tRNA methyltransferases, NSUN2 and METTL1, strongly influences 5-FU sensitivity in human cancer cells." (PMID 25233213, 2014). "To evaluate its function in ATC drug resistance, we examined correlations between the expression of 12 m5C regulators [NSUN2-7, TRDMT1 (writers); ALKBH1, TET2, ALKBH3 (erasers); YBX1 and ALYREF (readers)] and drug sensitivity in the Cancer Therapeutics Response Portal (CTRP)." (PMID 40083919, 2025). "The NSUN2 lactylation promotes its enzymatic activity to catalyze m5C modification on target GCLC mRNA, leading to upregulated GCLC expression and GSH synthesis rendering cancer cells resistant to ferroptosis." (PMID 39742570, 2025). "In summary, our findings suggest that NSUN2 is significantly differentially expressed in OSCC and could be an essential factor in the development of cancer." (PMID 41436732, 2025). "Notably, DNMT1, NSUN2, and TET2 showed consistent positive correlations with WDHD1 expression across all types of cancers." (PMID 37759234, 2023).
cancer (continued). "Studies have confirmed that high NSUN2 expression is a poor prognostic factor in GC and HNSC, which highlights that NSUN2 serves as a poor prognostic factor and can be used as a pan-cancer biomarker." (PMID 37769000, 2023). "Additionally, the mc5 tRNA methyltransferases NSUN2 and DNMT2, which also play a role in translation regulation, have been found to be overexpressed in many cancer types including oral, colon and breast cancer cells, respectively." (PMID 35721477, 2022). "However, deletion of NSUN2 and METTL1 in HeLa cells increased sensitivity to the anti-cancer drug 5-fluorouracil." (PMID 35721477, 2022). "As GRB2 has been suggested to be a therapeutic target for cancers by targeting its SH2/SH3 domains, it may be interesting to further study the synergistic anticancer effect of GRB2 and NSUN2-mediated m5C modification in ESCC." (PMID 34345012, 2021). "Many studies have confirmed that NSUN2 and NSUN6 are related to cancer tumorigenesis." (PMID 33928086, 2021). "NSUN2 may affect these signaling pathways by regulating the binding of H19 RNA to G3BP1 and then affect the progression and malignancy of cancer cells." (PMID 32978516, 2020). "In addition to upregulation of Elongator, ALKBH8 and thiolase genes CTU1 and CTU2 genes, other tRNA modification genes, including NSUN2 (m5C) and METTL1 (m 7G) also become overexpressed in human cancers." (PMID 30597914, 2018). "NSun2 is a nucleolar protein that is regulated by Aurora B kinase and promotes cell division by stabilizing the mitotic spindle in cancer cell lines, yet this function seems independent of its methyltransferase activity and has yet to be confirmed in vivo." (PMID 25014650, 2014). "Overexpression of tRNA-modifying enzymes NSUN2 and METTL1 is widely observed among human cancers." (PMID 25233213, 2014). "Using the Cancer Cell Line Encyclopedia (CCLE) dataset, which comprises 545 drugs and 829 cell lines with IC50 AUC data and gene expression profiles, we observed that NSUN2 expression in ATC cells was positively correlated with the IC50 values of various chemotherapy drugs and TKIs." (PMID 40083919, 2025). "Regardless, the mutual promotion between NONO and NSUN2 may aggravate the cancer progression since both serve as oncogene." (PMID 40033337, 2025). "Subsequent evaluation of NSUN2 protein levels in 174 clinical samples (131 tumors and 43 paracancerous tissues) from our hospital (SYSU-TFAH cohort) using IHC staining demonstrated predominant expression in the cancer cell nucleus and partial expression in the cytoplasm within HNSCC tissues." (PMID 39595099, 2024). "5-methylcytosine (m5C) modification, which is mainly induced by the RNA methyltransferase NSUN2 (NOP2/Sun domain family, member 2), is an important chemical posttranscriptional modification in mRNA and has been proven to play important roles in the progression of many cancers." (PMID 36792587, 2023). "Importantly, the lack of NSUN2 leaves cells in an undifferentiated and proliferation-inhibited state, which is required for tissue or cancer stem cell self-renewal." (PMID 36360287, 2022). "In this study we revealed that NSUN2 is not a critical regulator of cancer cell growth." (PMID 25233213, 2014). "Although NSUN2 overexpression does not act as oncogene, the likelihood that NSUN2 overexpression might confer a growth advantage or a cancer stem cell property in cancer cells remains." (PMID 25233213, 2014). "Thus, the combined activity of NSUN2 and METTL1 seems to be critical for 5-FU sensitivity of cancer cells, suggesting the presence of a conserved RTD-like pathway regulated by NSUN2 and METTL1 for participating in a surveillance system for tRNA quality control in human." (PMID 25233213, 2014).
cancer (continued). "Taken together, our findings convincingly elucidate the signaling axis of NAA10-NSUN2-GCLC that potently antagonizes the ferroptosis under acidic condition, and therefore, targeting NSUN2 lactylation might be an effective strategy in improving the prognosis of cancer patients." (PMID 39742570, 2025). "Furthermore, the observation that the cytotoxic effect of 5-FU in yeast is enhanced by heat stress in a trm8 mutant strain leads us to the hypothesis that nonessential tRNA modifications catalyzed by NSUN2 and METTL1 impacts the efficiency of 5-FU treatment in human cancer cells." (PMID 25233213, 2014).
neurodevelopmental disorder (10 papers, 2017 to 2025). A behavioral and cognitive disorder with onset during the developmental period that involves impaired or aberrant development of intellectual, motor, or social functions. "Loss-of-function mutations in NSUN2 cause neurodevelopmental disorders, underscoring its importance." (PMID 40870000, 2025). "Neurodevelopmental disorders caused by the NSUN2 gene exhibit a wide range of complex clinical symptoms." (PMID 38643142, 2024). "Mutations in NSUN3 and NSUN2 are linked to mitochondrial encephalopathy, epilepsy, and neurodevelopmental disorders, emphasizing the importance of mt-tRNAMet methylation and m5C in neurodevelopment." (PMID 39061374, 2024). "Mutations in NSUN2, a gene crucial for the m5C modification of tRNA, have been implicated in various neurodevelopmental disorders." (PMID 39061374, 2024). "Mutations in the NSUN2 gene have been associated with neurodevelopmental disorders in humans." (PMID 31276587, 2019). "Loss of function mutations in NSUN2 underlie several neurodevelopmental disorders." (PMID 30704115, 2019).
infection (8 papers, 2014 to 2025). The state of being infected such as from the introduction of a foreign agent such as serum, vaccine, antigenic substance or organism. "We only assessed viral gRNA m5C methylation in the cell infection model and determined the effects of NSUN2-KO and RNA m5C site mutation on HCV life cycle." (PMID 39957240, 2025). "Then, we used SARS-CoV-2 Beta variant (B.1.351) infection mice model to further verify the NSUN2-mediated regulation of SARS-CoV-2 infection in vivo." (PMID 39110796, 2024). "Using the SARS-CoV-2 Beta variant (B.1.351)–infected mouse model, we found that endogenous Nsun2 mRNA levels also decreased in SARS-CoV-2 Beta variant (B.1.351)–infected group [4 days post infection (dpi)] compared to the uninfected group (Mock)." (PMID 39110796, 2024). "Finally, in a study comparing gene expression in the duodenum following natural infection of lambs from the Perendale selection lines used in this study, NSUN2 was found to be more highly expressed in susceptible animals." (PMID 25074012, 2014). "Supported by both cellular and mouse infection models, our findings reveal that NSUN2-mediated m5C methylation of HCV RNA and host mRNAs facilitates viral RNA replication." (PMID 39957240, 2025). "Confocal immunofluorescence analysis showed that HCV Core protein expression decreased in NSUN2-KO Huh7.5.1 cells at 48 h post infection compared to that in WT cells." (PMID 39957240, 2025). "To further confirm the regulatory function of NSUN2 in NSCLC progression, we stably constructed NSCLC cell lines overexpressing NSUN2 using lentiviral infection." (PMID 38403250, 2024). "The results show that the antigens and RNAs levels of HBV decreased after NSUN2 depletion at 3 and 9 days post-infection." (PMID 38048324, 2023). "NSUN2 functions as a proviral effector facilitating Flaviviridae replication, concomitant with marked elevation in its expression and global m5C RNA methylation within immune-relevant tissues upon infection." (PMID 41343601, 2025). "Supported by both cellular and mouse infection models, our findings suggest that NSUN2 may be a potential new therapeutic target for HCV or other Flaviviridae virus infections." (PMID 39957240, 2025). "Notably, a homologous mechanism is operative in Orthomyxoviridae infection, indicating evolutionary convergence on NSUN2 as a proviral effector." (PMID 41343601, 2025). "Additionally, when C2017A mutation was introduced solely into the core expressing plasmid, we observed a slight increase in endogenous NSUN2 expression after transfection, which is consistent with the results after viral transfection or infection." (PMID 38048324, 2023). "To investigate whether these results could be repeated in the HBV infection system, we analyzed the HBV expression and replication levels in NSUN2-depleted HepG2-NTCP after infection with HBV." (PMID 38048324, 2023). "Interestingly, we also found that the endogenous expression of NSUN2 increased after HBV transfection or infection, during which HBV core protein may function as the key regulator." (PMID 38048324, 2023). "Compared with WT HepG2-NTCP cells and primary human liver cells, cells in which NSUN2 had been knocked down had decreased HBV replication level, and the infection and replication abilities of the mutant virus were significantly impaired in the cells." (PMID 41462962, 2025). "Infection with Sendai virus, vesicular stomatitis virus, herpes simplex virus 1, Zika virus, or SARS-CoV-2 reduced endogenous NSUN2 levels." (PMID 41462962, 2025). "It has been reported that during Sendai virus (SeV) or Vesicular stomatitis virus (VSV) infections in HEK293 cells, NSUN2 acts as a negative regulator of the interferon (IFN) response through mediating IRF3 mRNA m5C modification." (PMID 39957240, 2025).
infection (continued). "At 48 hpi, m5C RNA-BS-seq revealed that although m5C positional distribution remained largely unchanged, NSUN2 depletion led to a substantial reduction in m5C abundance, more pronounced under JEV (67.98%) than CSFV (47.27%) infection." (PMID 41343601, 2025). "NSUN2-mediated m5C methylation of SARS-CoV-2 RNA negatively regulates viral replication and the virulence of progeny viruses in the new infection." (PMID 39110796, 2024). "The endogenous expression of NSUN2 in HepG2 and PHHs increased after HBV transfection or infection, during which a positive feedback loop formed to promote HBV replication and expression." (PMID 38048324, 2023). "Further, we used the SARS-CoV-2 GFP/ΔN trVLP with NSUN2-mediated m5C methylation (normal m5C) and SARS-CoV-2 GFP/ΔN trVLP without NSUN2-mediated m5C methylation (low m5C) to infect Caco-2–N-mCherry cells and NSUN2 knockout Caco-2–N-mCherry cells at the same multiplicity of infection (MOI)." (PMID 39110796, 2024). "Besides, we also firstly demonstrate that NSUN2 inhibitors (SAH and sinefungin) could suppress HCV RNA replication and protein translation at a late stage (> 12 h post-infection), but not at an early stage of HCV infection." (PMID 39957240, 2025).
cardiovascular disease (2 papers, 2022 to 2025). "By searching for the potential targets of miR-877-3p, we found that among the potential targets regulated by miR-877-3p, GADD45g, NSUN2, YTHDF2 and MTUS1 have regulatory roles in the involvement of cardiovascular disease 30-32." (PMID 35928721, 2022).
mitochondrial disease (2 papers, 2019 to 2025). "To date, only NSUN2, NSUN3 and NSUN4 are known to be involved in methylation of rRNA and tRNAs in mitochondria, and mutations in mt-tRNA m5C RNA writer, NSUN3, are already recognised to cause mitochondrial disease." (PMID 39499421, 2025).
neurological disorders (2 papers, 2020 to 2023). "Therefore, further analysis will be required to uncover other salient roles of NSun2 on the post-transcriptional regulation of other non-coding small RNAs in AD and related neurological disorders." (PMID 36357715, 2023).
gastrointestinal tumours (1 paper, 2025). "Given that gastrointestinal tumours, particularly CRC, are directly exposed to a diverse range dynamic stimulatory factors, including nutrients, microorganisms, and drugs, this accordingly highlights the potentially complex nature of the regulatory mechanisms of NSUN2 in the progression of CRC." (PMID 40156167, 2025).
heart to (1 paper, 2025). "Based on these observations, we conclude that deprivation of cardiac Nsun2 abrogates the heart hypertrophic response to pathological stresses and predisposes the heart to failure." (PMID 39990213, 2025).
neuromuscular disease (1 paper, 2024). "In addition, they clarified that two patients had non-neuromuscular diseases, related to NSUN2 and POLR3A genes, respectively." (PMID 37989827, 2024).
NSUN2 also shares sentences with these, for which no sentence is quoted: Dubowitz syndrome (5 papers); developmental delay (2); eczema (2); heart diseases (2); idiopathic pulmonary fibrosis (2); skin cancer (2); adrenocortical carcinoma (1); brain disorder (1); Cerebellar atrophy (1); Cerebellar hypoplasia (1); cervical squamous cell carcinoma (1); dementia (1); diabetic retinopathy (1); Dias-Logan syndrome (1); ductal breast carcinoma in situ (1); ductal breast carcinomas (1); epilepsy (1); focal epilepsy (1); head and neck neoplasm (1); hematologic malignancies (1); hypospadias (1); invasive breast carcinoma (1); learning disabilities (1); malaria (1); male infertility (1); malignant glioma (1); oesophageal cancer (1); pancreatic adenocarcinoma (1); progressive supranuclear palsy (1); prostate tumor (1).
A further 6 diseases each share a sentence with NSUN2 in 1 paper.